ZNF396 (zinc finger protein 396)
Description:
Isoform 1 and isoform 2 act as DNA-dependent transcriptional repressors.
Synonyms: ZSCAN14; FLJ31213
Tractability: PROTAC: ubiquitination databases record sites on it.
Gene: Protein-coding gene on chromosome 18 (35,366,694 to 35,381,746, reverse strand). Ensembl gene ENSG00000186496.
Subcellular location: Nucleus (Isoform 1); Nucleus (Isoform 2); Cytoplasm
Gene Ontology:
Molecular function: sequence-specific double-stranded DNA binding; DNA-binding transcription factor activity, RNA polymerase II-specific; RNA polymerase II cis-regulatory region sequence-specific DNA binding; sequence-specific DNA binding
Biological process: regulation of transcription by RNA polymerase II; negative regulation of DNA-templated transcription
Cellular component: chromatin; nucleus; cytoplasm
Genetic constraint (gnomAD): Loss-of-function variants: 14 observed, 21.96 expected, observed/expected ratio (o/e) 0.64, 90% interval 0.42 to 1. The upper end of that interval is the gene's LOEUF score, 1, which puts it in group 4 of 6, group 1 being the genes least tolerant of losing a copy. Missense variants: 347 observed, 410.83 expected, observed/expected ratio (o/e) 0.84, 90% interval 0.77 to 0.92. Synonymous variants: 119 observed, 149.24 expected, observed/expected ratio (o/e) 0.8, 90% interval 0.69 to 0.93.
Homologues: Orthologues: chimpanzee ZNF396 (98% identical), pig ZNF396 (67% identical), dog ZNF396 (67% identical). Paralogues in human: ZNF24 (58% identical), ZSCAN12 (45% identical), ZNF397 (44% identical), ZSCAN30 (44% identical), ZSCAN23 (44% identical), ZKSCAN4 (43% identical), ZKSCAN8 (43% identical), ZSCAN31 (43% identical), ZKSCAN3 (42% identical), ZSCAN9 (42% identical), ZKSCAN1 (42% identical), ZNF232 (42% identical), and 18 more.
Diseases named in the same sentence as ZNF396 in open-access papers:
ZNF396 is named in the same sentence as 1 disease in open-access papers, as found by Europe PMC text mining. Sharing a sentence is not in itself a finding about the gene and the disease.
ZNF396 shares sentences with these, for which no sentence is quoted: cancer (1 paper).